UCP1 (uncoupling protein 1)
Diseases named in the same sentence as UCP1 in open-access papers (continued):
Sharing a sentence is not in itself a finding about the gene and the disease.
osteosclerosis (1 paper, 2019). Abnormally high bone density. "The failure of UCP1 deletion, in adipose tissue, to impact bone mass, indicates that cure of FF osteosclerosis by BAT does not involve uncoupled energy expenditure." (PMID 31233501, 2019).
ovarian tumors (1 paper, 2011). "UCP1 expression was increased in a small number (∼30%) of breast and ovarian tumors." (PMID 21935467, 2011).
overactive bladder (1 paper, 2021). Symptom of overactive detrusor muscle of the urinary bladder that contracts with abnormally high frequency and urgency. "Mirabegron is a β3-adrenergic agonist approved for the treatment of an overactive bladder, and treatment for 10 weeks induces UCP1 in obese and insulin-resistant individuals." (PMID 34832978, 2021).
pleomorphic liposarcoma (1 paper, 2019). Pleomorphic liposarcoma (PLS), the rarest subtype of liposarcoma (LS), is an aggressive, fast growing tumor located usually in the deep soft tissues of the lower and upper extremities. "UCP1 was not expressed in WAT or other adipose tumours with the exception a few tumour cells in pleomorphic liposarcoma." (PMID 31114671, 2019). "In this study we have shown that UCP1 is strongly expressed in BAT but not WAT and that, with the exception of all hibernomas and a minority of pleomorphic liposarcomas, UCP1 is not expressed in benign and maligant adipose tumours." (PMID 31114671, 2019).
prediabetes (1 paper, 2019). "Accordingly, IL-33 was directly associated with PRDM16 but not with UCP1 or COX7A1 in individuals with normoglycemia and T2D but not in those with prediabetes." (PMID 31073344, 2019). "Although IL-33 was not correlated with UCP1 or COX7A1, it was directly correlated with PR domain containing 16 (PRDM16) in individuals with normoglycemia (r = 0.5; P = 0.02; n = 20) and T2D (r = 0.38; P = 0.01; n = 43) but not in those with prediabetes." (PMID 31073344, 2019).
psoriasis (1 paper, 2025). An autoimmune condition characterized by red, well-delineated plaques with silvery scales that are usually on the extensor surfaces and scalp. "However, this is the first study to investigate the association between UCP1 and psoriasis, and the results provide important information for the literature." (PMID 40104293, 2025). "Simple logistic regression analysis showed that an individual with a UCP1 level below 7.561 ng/mL was 73% less likely (OR: 0.27, 95% CI: 0.08–0.94, p = 0.039) to have psoriasis than an individual with a UCP1 level above 7.561 ng/mL." (PMID 40104293, 2025). "In our study, we found that UCP1 levels in psoriasis patients (7.47 ± 1.38 ng/mL) were lower compared to the control group (8.42 ± 1.07 ng/mL)." (PMID 40104293, 2025). "Due to its ability to identify 66.67% of psoriasis patients at levels above 7.561 ng/mL and to differentiate 76.67% of healthy individuals at levels below that value, UCP1 can be considered as a potential marker in psoriasis." (PMID 40104293, 2025). "The mean UCP1 level was significantly lower in patients with psoriasis compared to healthy controls (7.47 ± 1.38 vs. 8.42 ± 1.07, p = 0.004)." (PMID 40104293, 2025). "Simple logistic regression analysis showed that an individual with a UCP1 value below 7.561 had a 73% lower probability (OR: 0.27, 95% CI: 0.08–0.94, p = 0.039) of developing psoriasis than an individual with a UCP1 value above 7.561." (PMID 40104293, 2025). "Since UCP1 could detect patients with psoriasis at an approximate rate of 77% with a cut-off value of >7.561 ng/mL, we consider it a potential biomarker candidate for psoriasis." (PMID 40104293, 2025). "According to the sensitivity (66.67%) and specificity (76.67%) of UCP1, it may be a valuable candidate marker in the diagnosis of psoriasis patients in symptomatic and asymptomatic phases." (PMID 40104293, 2025). "The effects of other inflammatory dermatological diseases on UCP1 levels are considered a separate research topic that could be studied in comparison to psoriasis." (PMID 40104293, 2025).
rhabdomyosarcoma (1 paper, 2019). A rare aggressive malignant mesenchymal neoplasm arising from skeletal muscle. "Another possible reason for some rhabdomyosarcomas expressing UCP1 is that brown fat and skeletal muscle have been shown to share a common developmental pathway." (PMID 31114671, 2019).
rheumatoid arthritis (1 paper, 2021). A chronic, systemic autoimmune disorder characterized by inflammation in the synovial membranes and articular surfaces. "Our objective was to investigate a connection between UCP1 expression and cardiovascular health in patients with rheumatoid arthritis (RA) in a longitudinal observational study." (PMID 34067093, 2021).
sarcoma (1 paper, 2019). A usually aggressive malignant neoplasm of the soft tissue or bone. "UCP1 expression in a few non-adipose soft tissue sarcomas may possibly reflect origin of tumour cells from a common mesenchymal stem cell precursor and/or developmental pathway." (PMID 31114671, 2019).
SHORT syndrome (1 paper, 2025). A rare disorder characterized by multiple congenital anomalies, including short stature, hyperextensibility of joints, ocular depression, Rieger anomaly and teething delay in which the cause of the disease is a mutation in PIK3R1 gene. "We provide conclusive evidence that the increased energy expenditure in a SHORT syndrome model is not caused by changes in physical activity, macronutrient oxidation, thermoregulation, or Ucp1-mediated energy dissipation in BAT." (PMID 40152560, 2025).
soft tissue tumours (1 paper, 2019). "Immunohistochemical staining of normal (axillary) BAT and subcutaneous/abdominal white adipose tissue (WAT) as well as a wide range of benign and malignant primary soft tissue tumours (n = 171) was performed using a rabbit polyclonal antibody to UCP1." (PMID 31114671, 2019). "UCP1 expression was not seen in any of the benign (non-adipose) soft tissue tumours examined, including those of smooth muscle, nerve sheath and vascular differentiation." (PMID 31114671, 2019). "UCP1 has also been found in other tissues (e.g. smooth muscle) but whether it is expressed in non-adipose benign and malignant soft tissue tumours is unknown." (PMID 31114671, 2019). "In addition, as UCP1 has been reported in other cell types, we have examined whether UCP1 is expressed in a wide range of non-adipose benign and malignant soft tissue tumours." (PMID 31114671, 2019).
thyroid hormone resistance (1 paper, 2026). "Collectively, these findings identify fructose as a potent inhibitor of brown adipogenesis, suppressing THR-dependent UCP-1 expression by inducing thyroid hormone resistance through a defect in THR-mediated transcriptional regulation." (PMID 42237874, 2026).
triple-negative breast carcinoma (1 paper, 2022). An invasive breast carcinoma which is negative for expression of estrogen receptor (ER), progesterone receptor (PR), and human epidermal growth factor receptor 2 (HER2). "The present study showed that UCP1 regulates the proliferation and metastasis of triple-negative breast cancer (TNBC) in vitro and in vivo by activating mitophagy and pyroptosis." (PMID 35541900, 2022). "Moreover, MDA-MB-231 transfected with UCP1 also showed less quantity and smaller volume of secondary sites, demonstrating the regulatory potential of UCP1 on metastasis of triple-negative breast cancer in vivo." (PMID 35541900, 2022). "Furthermore, we detected the UCP1 expression of protein and mRNA on MCF10A (an immortalized standard breast cell line) and in BT549 (a triple-negative breast cancer cell line)." (PMID 35541900, 2022).
viral infection (1 paper, 2023). "In addition, we aimed to assess some of the effects that viral infection has on the metabolism of these cells, including changes in uncoupling protein 1 (UCP1) expression and lipid organization." (PMID 37766234, 2023).
vitamin D-resistant rickets (1 paper, 2020). "A previous study that using human patient samples from individuals with hereditary vitamin D-resistant rickets showed that Ucp1 expression is negatively regulated by the Vdr in human cells, but the co-activator interaction is probably not required for the inhibitory activity." (PMID 32452516, 2020).
tumor (90 papers, 2002 to 2026). "The decreased WAT mass in vehicle-treated OSCR2 tumor-bearing mice was associated with upregulation of the thermogenic protein Ucp1, which causes energy dissipation as heat (thermogenesis) rather than through ATP generation." (PMID 41315757, 2026). "The decreased WAT mass in vehicle-treated OSCR2 tumor-bearing mice was associated with the upregulation of the thermogenic protein Ucp1, which causes energy dissipation as heat (thermogenesis) rather than through ATP generation." (PMID 40964365, 2025). "In response to tumour growth, eWAT exhibited higher expression of Ucp1 and Ppargc1a, encoding UCP1 and PGC1α, respectively, which are involved in the adipocyte metabolic switch to a thermogenic fat‐burning state termed ‘browning’." (PMID 39971710, 2025). "Our previous study showed that lipid browning mediated by PLCL1/UCP1 promotes tumor cell “slimming” and causes abnormal lipid accumulation, which represses the progression of ccRCC." (PMID 38263248, 2024). "Immunoblots confirmed the high levels of 75-kDa glucose regulatory protein (GRP75), encoded by Hspa9, and UCP1 proteins in the iWAT of YES2 tumour-bearing mice from T-1 to T-3." (PMID 39327432, 2024). "Remarkably, GPR81 deficiency blocked tumour-induced UCP1 expression, indicating suppressed iWAT browning." (PMID 38499763, 2024). "Similarly, in the present study, the association of UCP1 with the tumor immune microenvironment in BC was minimal in comparison with UCP2." (PMID 35874806, 2022). "The KEGG enrichment results revealed the association of UCP1 with multiple tumor metabolic pathways, including upregulation of taurine and hypotaurine metabolism, arachidonic acid metabolism, glycerophospholipid metabolism, and tyrosine metabolism, and downregulation in oxidative phosphorylation." (PMID 35874806, 2022). "A previous study has shown that UCP1 promotes the catabolism of cancer-associated fibroblasts and cancer-associated adipocytes to provide metabolic energy to cancer cells thereby giving a tumor growth advantage." (PMID 35874806, 2022). "Moreover, UCP-1 was overexpressed in cancer-associated fibroblasts resulting in the release of ATP-rich vesicles by activating autophagy, and our study verified that UCP-1 was also highly expressed in cancer-associated adipocytes after the uptake of tumor exosomes." (PMID 31500658, 2019). "In addition, the UCP1 hyperexpression by tumor-associated stromal fibroblasts may potentiate cancer growth by providing high-energy nutrients in a paracrine fashion." (PMID 27853670, 2016). "In contrast, tumor-secreted factors including parathyroid hormone-related protein (PTHrP) and interleukin-6 aberrantly induce uncoupling protein 1 (UCP1) expression and β3-adrenergic signaling, driving lipolysis and energy wasting in CAC." (PMID 41848823, 2026). "For example, BAT overexpression of translationally controlled tumor protein enhances systemic metabolic homeostasis through UCP1-mediated thermogenesis." (PMID 41551882, 2026). "To show that this approach can work with another adipocyte cell line, we repeated these experiments for MCF-7 xenografts with UCP1-CRISPRa primary adipocytes and found that they also significantly suppressed tumor growth." (PMID 39905264, 2025). "IHC results of subcutaneous tumors also unveiled that the expression of LCOR, PLCL1 and UCP1 increased and the tumor malignant index Ki67 decreased after LCOR overexpression." (PMID 40083699, 2025). "These images provide evidence of the presence of brown adipocytes, marked by UCP-1 expression, within the periprostate tumor fat." (PMID 40437336, 2025). "UCP-1 levels were specifically targeted using IF labeling, indicating the presence of brown adipocytes within the periprostate tumor fat." (PMID 40437336, 2025). "Using immunofluorescence, we examined additional tumor marker genes and found that all tumors co-transplanted with UCP1-CRISPRa-modulated human adipose organoids had markedly reduced Ki67+ cells." (PMID 39905264, 2025).
tumor (continued). "The compelling evidence that both exogenous mitochondrial uncouplers and UCP1 activation in BAT impair tumor growth presents a paradox when compared with the frequent upregulation of endogenous UCPs—particularly UCP2—in human cancers." (PMID 40983641, 2025). "The immunofluorescence (IF) images demonstrated the presence of brown adipocytes with detectable UCP-1 signals within periprostate tumor fat." (PMID 40437336, 2025). "Immunofluorescence, H&E staining, and immunohistochemistry revealed the presence of brown adipocytes, marked by uncoupling protein 1 expression, in periprostate tumor fat." (PMID 40437336, 2025). "To show that this approach works with other adipocyte lines, we also upregulated UCP1 in human adipocytes differentiated from primary preadipocytes and found that they inhibit tumor growth of all five cancer cells." (PMID 39905264, 2025). "The functional proteins (AMPKα, HSL, p38) involved in lipolysis and uncoupling protein 1 involved in energy expenditure were overexpressed in eWAT tissues of C26 tumor-bearing mice, and were reversed by Z526 treatment." (PMID 39759112, 2025). "One proposed function is the UCP1-dependent induction of a catabolic state known as “tumour slimming,” characterized by suppressed tumour progression." (PMID 40120980, 2025). "In renal cell carcinoma, perirenal adipose tissue adjacent to the tumour exhibits markedly higher UCP1 expression compared to normal perirenal fat." (PMID 40943351, 2025). "This intervention was initiated at the T-1 timepoint, coinciding with the observation of white adipose tissue atrophy and elevated expression of GRP75 and UCP1 in YES2 tumour-bearing mice." (PMID 39327432, 2024). "Subsequently, we assessed UCP1 mRNA levels in tumor tissues and adjacent normal tissues in paired clinical samples using RT-qPCR." (PMID 38245780, 2024). "NuF blocked LLC tumor-induced PTHrP and expression of thermogenic factor UCP1 and lipolytic enzymes (ATGL and HSL) in WAT." (PMID 39273055, 2024). "We also found that the novel “tumor slimming” pathway mediated by melatonin/PGC1A/UCP1 exhibits prognostic potential in ccRCC." (PMID 38263248, 2024). "UCP1-dependent BAT activation by cold exposure significantly inhibits tumor growth by reducing blood glucose levels and increasing glycolytic metabolism in CRC tumor-bearing mouse models." (PMID 39125923, 2024). "To test thermogenesis as the energy expenditure mechanism for mirabegron-suppressed tumor, we applied Ucp1−/− mice in C57BL/6 background for tumor implantation." (PMID 37993438, 2023). "Epididymis WAT showed UCP-1 expression in tumor-free mice, while it was downregulated in Lewis lung carcinoma-bearing mice regardless of treatment with GW9508." (PMID 36900198, 2023). "A groundbreaking discovery in our present study is that genetic deletion of UCP1 in mice completely abrogates tumor suppression by mirabegron." (PMID 37993438, 2023). "Uncoupling protein 1 (UCP1) is elevated in adipocytes adjacent to BC tumor cells, and its expression is found to be positively correlated with MCT4 expression." (PMID 36765683, 2023). "This fact was evidenced by the considerable reduction in tumour development following the elimination of BA-tilted cells that were positive for UCP1 or Myogenic Factor 5 (MYF5)." (PMID 37886942, 2023). "There was much lower VHL level but endowed with higher HIF1A, LEPTIN, UCP1 and phosphorylated HSL protein expression in tumour associated adipose tissue as well." (PMID 37620316, 2023). "Age, visceral adipose tissue (VAT) area and body mass index (BMI) predicted tumour-sided perirenal fat area (R2 = 0.584), which presented upregulated UCP1 expression by 27-fold (P = 0.026) and smaller adipocyte areas, compared with subcutaneous depot." (PMID 36402906, 2022). "UCP1 was associated with the impaired glucose metabolism, while UCP2 with enhanced anti-tumor immunity." (PMID 35874806, 2022).